DGKA (diacylglycerol kinase alpha)
Diseases named in the same sentence as DGKA in open-access papers (continued):
Sharing a sentence is not in itself a finding about the gene and the disease.
cancer (continued). "Despite the progress in linking the function of DGKα with the development of cancer and other diseases, it is still challenging to study their biology." (PMID 37392305, 2023). "Recent studies have noted its function as a particular inhibitor of diacylglycerol (DAG) kinase α (DGKα), which can inhibit the progression of certain cancers and enhance immunotherapies." (PMID 37392305, 2023). "Bearing in mind the potential therapeutic benefits of targeting DGKα, here, the role of DGKα in cancer and T cell biology with a focus on the modulation of its enzymatic properties by membrane shape is reviewed." (PMID 36358678, 2022). "DGKα has been found to regulate signaling pathways integral to cancer, despite being only one member of the large DGK family—suggesting a general lack of redundant function across the family." (PMID 35267577, 2022). "Since DGKα inhibition can kill cancer cells and enhance T-cell function, the development of inhibitors has been focused on, and activators have received less attention." (PMID 36296376, 2022). "Here, the modulation of DGKα enzymatic activity and substrate acyl chain specificity by membrane shape and its potential implications in cancer and immune cell biology are reviewed." (PMID 36358678, 2022). "Independently of this, inhibition of DGKα also releases T-cells from anergy and allows for greater immune clearance of cancer cells." (PMID 36358678, 2022). "DGKA is the family member of conserved membrane lipid kinases and has been involved in human cancers." (PMID 35957912, 2022). "It has been proposed that the DGKα role in cancer and immune cell biology is due to its ability to regulate the levels of these two lipid messengers." (PMID 36358678, 2022). "Diacylglycerol kinase α (DGKα) has gathered great attention as a potential molecular target in immunotherapy because of its role in cancer proliferation and immunosuppression." (PMID 36358678, 2022). "Bearing in mind the potential therapeutic benefits of targeting DGKα, it is here discussed the role of DGKα in cancer and T cell biology." (PMID 36358678, 2022). "Efforts are underway to further develop such compounds, likely driven in large part by the appeal of the immunotherapeutic potential of DGKα inhibitors in combination regimens for cancer." (PMID 35267577, 2022). "In the following paragraphs, a discussion of a few examples of the interplay between DGKα and membrane remodeling events in T cell and cancer biology will be discussed." (PMID 36358678, 2022). "DGKα is also highly expressed in various cancer cells, where it has been shown to be involved in cancer cell survival, proliferation, migration, and invasiveness." (PMID 36358678, 2022). "On the one hand, DGKα has been found to increase the survival, proliferation, migration, and invasion of some cancers and, therefore, its inhibition has been shown to prevent tumorigenesis." (PMID 36358678, 2022). "DGKα-selective inhibitors are expected to be dual effective drugs (i.e., ideal cancer therapy medicines) because (Section 3 and Section 4), they simultaneously suppress cancer cell proliferation and boost immune reactions, including anticancer immunity." (PMID 34680338, 2021). "As PA activates PKCζ, Raf, and PDE, it is likely that PA generated by DGKα plays an important role in the proliferation/antiapoptosis of cancer cells." (PMID 34680338, 2021). "Taken together, inhibition of DGKα suppresses cancer cell proliferation, enhances cancer cell apoptosis, and attenuates cancer cell invasion." (PMID 34680338, 2021). "The potential of DGKα as a therapeutic target in several cancers has been demonstrated by us and others, and more potent and specific DGKα inhibitors are in development at large pharmaceutical companies." (PMID 34804012, 2021). "Taken together, these findings identify a novel immune-regulatory checkpoint function of DGKα in macrophages with potential implications for wound healing, cancer therapy, and other settings." (PMID 34804012, 2021).
cancer (continued). "The combination therapies with DGKα-specific inhibitors and anti-PD-1/PD-L1 antibodies, if established, will provide survival benefits for much greater numbers of advanced cancer patients." (PMID 34680338, 2021). "In this article, we review the properties of DGKα and its roles in cancer cell proliferation and apoptosis, and anticancer immunity." (PMID 34680338, 2021). "It is possible that DG supply enzymes, which provide distinct DG species upstream of DGKα, are different from each other in cancer and T cells." (PMID 34680338, 2021). "DGKα-selective inhibitors would be dual effective compounds (i.e., ideal cancer therapy candidates) because they attenuate cancer cell proliferation and simultaneously enhance immune responses, including anticancer immunity." (PMID 32947951, 2020). "Further evidence for an anti-apoptotic and proliferation-enhancing activity of DGKA in cancer cells derived from different cancer entities is reported using selective inhibitors of DGKA." (PMID 32477950, 2020). "Currently, DGKα holds much promise in cancer therapy, as its inhibition presents toxicity in various cancer, but not normal human cells." (PMID 32722576, 2020). "In other cancer cells, such as K562 human erythroleukemia cells, DGKα can modulate cell cycle progression by influencing the phosphorylated status of pRb, which subsequently induces cell cycle arrest by impairing the G1/S transition." (PMID 32722576, 2020). "Apart from T-cell regulation, DGKα also plays a role in cancer, mediating numerous aspects of cancer cell progression including survival, migration and invasion of cancer cells." (PMID 31690133, 2020). "The pro-tumoral hypoxic and immunosuppressive TME upregulates DGKα in the cancer and infiltrating T cells." (PMID 32962151, 2020). "Both observations were found to be specifically active in malignant cells and make DGKA an exciting target in cancer therapy." (PMID 32477950, 2020). "Recently, increasing attention has been paid to its α isozyme (DGKα) as a potential target for cancer immunotherapy." (PMID 30128205, 2018). "The link with DGKs is provided by the observation that: i) aPKC binds to and is activated by PA and ii) their localization at the invasive protrusions of cancer cells is promoted by DGKα-produced PA." (PMID 27965956, 2016). "Surprisingly, both DGKα and ζ also play a key role in cancer-cell survival, acting at either the plasma membrane, intracellular organelles, or the nucleus." (PMID 27965956, 2016). "Recent studies demonstrated a central role for DGKα in sustaining oncogenic traits in several types of cancer." (PMID 26302180, 2015). "DGKα has been studied in several cancer models, where experimental evidence has shown that it mediates various aspects of cancer cell progression." (PMID 25339152, 2014). "Our data reinforce previous reports supporting a positive function of DGKα in cancer, and also provide a mechanistic link by showing that DGKα contributes to Src activation." (PMID 25339152, 2014). "Our results suggested that DGKα participates in a central node that promotes cancer cell growth in a 3D context." (PMID 25339152, 2014). "Together these data suggest that the crosstalk between the PI3K/Akt/FoxO and Src pathways via DGKα provides cancer cells with a mechanism to adapt and subvert the deleterious effects of PI3K/Akt inhibition." (PMID 25339152, 2014). "DGKα-PA production activates phosphodiesterase activity, that controls cAMP levels and the expression of cAMP responsive genes critical for cancer cell survival including mTOR and HIF-1." (PMID 25339152, 2014). "The expression of myr-DGKα drives pseudopodial extension by stimulating RCP-mediated recycling of β1 integrin in A2780 carcinoma cells." (PMID 24887021, 2014). "Indeed, analyses of cancer databases, including The Cancer Genome Atlas, have revealed DGKα, DGKγ, DGKδ, DGKε, and DGKζ overexpression in AML, although without a clear correlation to specific subtypes." (PMID 41227366, 2025).
cancer (continued). "Among the different upregulated genes, we especially examined DGKα, which had the least gene expression level dispersion within each group, and previous studies have suggested its involvement in tumorigenic activity in other types of carcinomas." (PMID 40013327, 2025). "It has been reported that DGKα inhibition induces cancer‐cell apoptosis." (PMID 38716625, 2024). "Because Ki‐67 staining positivity in cancer cells is known to be a proliferation marker, increased DGKα expression in ICC may contribute to the proliferation of ICC." (PMID 38716625, 2024). "So, DGKα has been thought of as an important cell growth factor in cancers." (PMID 38716625, 2024). "DGKα inhibition is considered a novel cancer therapeutic target." (PMID 38716625, 2024). "However, further studies are required to elucidate signal transduction through the DGKα–16:0/16:0-PA–HSP27 pathway during cancer cell proliferation and cancer progression more in detail and how DGKα has cancer- and T-cell-selective functions." (PMID 36791913, 2023). "Our findings suggest that combining Ras pathway inhibitors with DGKα inhibitors may provide even greater efficacy against Ras-driven cancers, as well as decrease unwanted side effects and reduce the development of drug resistance." (PMID 36861754, 2023). "Therefore, there is the possibility that SFA/MUFA-PAs produced by DGKα activate HSP27 in cancer cells." (PMID 36791913, 2023). "Therefore, it is possible that DGKα utilizes multiple pathways to promote the aggressiveness of cancer cells." (PMID 36791913, 2023). "To analyze whether HSP27 is substantially expressed in T cells, where DGKα plays roles different from cancer cells, we next examined the expression levels of HSP27 in Jurkat T cells by Western blotting." (PMID 36791913, 2023). "Elevated levels of DGKα and PA are related to cancer initiation and progression." (PMID 36791913, 2023). "Future studies addressing these challenges might help build a more global understanding of the molecular mechanisms governing the biological role of DGKα, specifically in cancer and immunosurveillance." (PMID 36358678, 2022). "However, contrary to other reviews on the topic, here the focus of the discussion will be on the modulation of DGKα enzymatic activity and substrate acyl chain specificity by the membrane shape and its potential implications in cancer and immune cell biology." (PMID 36358678, 2022). "This is certainly true for cancer, in which DGKα inhibition may not only have direct action against cancer cells but also stimulate the immune system to better attack cancers." (PMID 35267577, 2022). "This is because the silencing of DGKα activity provides a two-pronged attack on cancer cells." (PMID 36358678, 2022). "If proven true, this added immune benefit of DGKα inhibition could be particularly relevant for cancers such as GBM that typically include large numbers of macrophages and macrophage analogs, a group that also includes pancreatic cancer." (PMID 35267577, 2022). "A recent report indicates anti-cancer synergy with the combination of DGKα inhibition and anti-PD1 checkpoint inhibitor activity, and this regimen may also have promise for GBM." (PMID 35267577, 2022). "The inhibition of DGKα prevents cancer cell proliferation by promoting apoptosis of cancer cells." (PMID 36358678, 2022). "As DGKα is associated with cancer progression and DG is a potential LG MGM biomarker, future studies must investigate the plasma levels of DGKα and DG and their role in cancer development." (PMID 36613836, 2022). "In cancer cells, it is well known that DGKα prevents apoptosis via various signaling pathways, followed by PA production, suggesting the involvement of DGKα in the prevention of apoptosis of podocytes by green tea polyphenols, especially EGCG." (PMID 36296376, 2022).
cancer (continued). "This might lead to a better understanding of the modulation of these effectors by DGKα, which, in turn, could broaden our understand of the role of DGKα in cancer and immunosurveillance." (PMID 36358678, 2022). "DGKα inhibitors may be particularly well-suited for such combinations, with potential to enhance the activity of numerous therapies with direct anti-cancer activity but also immunotherapies." (PMID 35267577, 2022). "On the other hand, DGKα has been shown to decrease activation and increase anergy, a hypo-responsive state, in T cells and, therefore, its inhibition has been shown to incite powerful T cell responses leading to greater immune clearance of cancer cells." (PMID 36358678, 2022). "Hence, suppression of DGKα activity has the promise of having a dual activity against cancer by both unleashing T cell activity and inhibiting proliferation of cancer cells, the latter being proposed to be a consequence of increased apoptosis of these cells." (PMID 36358678, 2022). "What is the difference in DGKα functions between T lymphocytes and cancer cells?" (PMID 34680338, 2021). "Therefore, a DGKα-specific inhibitor is expected to be a dual effective anticancer treatment that inhibits cancer cell proliferation and simultaneously enhances T cell functions." (PMID 34680338, 2021). "Therefore, the synergistic effect of DGKα inhibition and PD-1/PD-L1 blockade provides a promising strategy to strengthen the efficacy of immunotherapy in the treatment of cancer." (PMID 34680338, 2021). "Therefore, DGKα-selective inhibitors are expected to be ideal anticancer medicines because the inhibition of DGKα suppresses cancer cell proliferation and simultaneously activates T cell function." (PMID 34680338, 2021). "More potent and specific DGKα inhibitors are in development as adjuncts for cancer immunotherapy, and these findings could extend their utility beyond the cancer setting." (PMID 34804012, 2021). "Therefore, the inhibition of DGKα activity is widely considered to enhance T cell proliferation/functions, which provide boosted immune surveillance and cancer immunity." (PMID 34680338, 2021). "Taken together, DGKα inhibition provides a promising new treatment strategy for refractory cancers." (PMID 34680338, 2021). "DGKα acts as an antiapoptosis/proproliferation factor in cancer cells." (PMID 34680338, 2021). "It is important to know how DGKα expression is regulated in cancer cells." (PMID 34680338, 2021). "Therefore, a DGKα-specific inhibitor is expected to be a dual effective anticancer treatment that inhibits cancer cell proliferation and simultaneously activates T cell function." (PMID 34680338, 2021). "DGKα inhibition would be especially appealing if it were able to not only directly attack cancer cells and boost T and NK cell activity, but also improve macrophage activity against cancer cells." (PMID 34804012, 2021). "Moreover, synergistic effects of DGKα inhibition and PD-1/PD-L1 blockade would provide a promising new strategy for refractory cancer therapy." (PMID 34680338, 2021). "In cancer cells, PA produced by DGKα plays an important role in proliferation/antiapoptosis." (PMID 34680338, 2021). "Therefore, the inhibition of DGKα activity is expected to suppress the progression and proliferation of these cancers." (PMID 34680338, 2021). "Additionally, some cancers are dependent on DGKα-regulated pathways, which promote cancer cell survival." (PMID 32962151, 2020). "Therefore, the inhibition of DGKα activity is thought to enhance T cell activity, which governs cancer immunity." (PMID 32947951, 2020). "The role of DGKα in the generation of cancer-associated fibroblasts in the TME has not been elucidated." (PMID 32962151, 2020). "Besides being in good agreement with the notion that DGKα is required for cancer cells migration, this observation indicates that our new DGKα inhibitors reduce cancer cell motility, suggesting a potential utility in a metastasis setting." (PMID 31690133, 2020).
cancer (continued). "Several studies have reported that DGKα is involved in cancer progression." (PMID 32962151, 2020). "For these reasons, there are several reports suggesting that DGKα may be a promising therapeutic target in cancer therapy." (PMID 32722576, 2020). "However, recent studies have also demonstrated the anti-tumoral effect of DGKα in different cancer types." (PMID 32962151, 2020). "Therefore, in addition to DGKα, DGKζ acts as a suppressor of T cell functions and its inhibitors are expected to be useful for cancer immunotherapy." (PMID 32947951, 2020). "Moreover, it has been noted that DGKα activates angiogenesis signaling and that this isozyme plays a key role in cancer cell migration." (PMID 32947951, 2020). "Notably, some DGK isoforms, such as DGKα, have been reported to possess promising therapeutic potential in cancer therapy." (PMID 32722576, 2020). "In addition, this observation supports DGKA as a potential therapeutic target for cancer and fibrosis treatment." (PMID 32477950, 2020). "Therefore, if a DGKα-selective inhibitor is identified and developed, it would reversely attenuate cancer cell proliferation and simultaneously activate T cell function and can be a dual effective compound." (PMID 27583247, 2016). "Therefore, the suppression of DGKα activity is expected to inhibit the progression of these cancers." (PMID 27583247, 2016). "The contribution of DGKα to SW480 growth in 3D suggests that this enzyme could be of interest for cancer therapy." (PMID 25339152, 2014). "In addition to PA mediated Src regulation, others have shown that DGKα-generated PA contributes to the survival and invasive properties of cancer cells by several mechanisms." (PMID 25339152, 2014). "Nonetheless the mechanisms that underlie DGKα specific contribution to cancer survival have not been elucidated." (PMID 25339152, 2014). "Our findings indicate that DGKα might be an effective target for anti-cancer therapies, alone or in combination with other widely used inhibitors." (PMID 25339152, 2014). "Many reports support a positive role for the DGKα isoform in cancer progression." (PMID 25339152, 2014). "However, the molecular pathways by which DGKα controls carcinoma formation and metastatization are poorly known." (PMID 24887021, 2014). "Therefore, DGKα has reverse roles in T cells (attenuator) and cancer cells (enhancer)." (PMID 36791913, 2023). "Therefore, this expression pattern may explain at least in part how DGKα plays reverse roles in T cells (attenuator) and cancer cells (enhancer)." (PMID 36791913, 2023). "Thus, low-dose trametinib combined with ritanserin, or with more selective DGKα inhibitors, is a novel anti-cancer combination therapy that could be developed to target human mammary cancers, as well as other human Ras-driven polarity-impaired cancers." (PMID 36861754, 2023). "In T cells and cancer cells, serum starvation led to the specific production of saturated and monounsaturated 16 carbon atoms PA species by DGKα, suggesting that these molecular species of PA might have been produced in the nucleus in non-proliferative conditions." (PMID 36358678, 2022). "Therefore, it is likely that DGKα expression is differently regulated in immune and cancer cells." (PMID 34680338, 2021). "Therefore, we hypothesized that attenuation of DGKζ synergistically augments the enhancing effects of DGKα inhibition on cancer cell apoptosis and T cell function." (PMID 34680338, 2021). "Thus, it is speculated that DGKα-dependent consumption of DG and the production of PA dominantly affect T cells and cancer cells." (PMID 34680338, 2021). "In addition to cancer cells, DGKα is abundantly expressed in T cells and the thymus." (PMID 34680338, 2021). "Indeed, a DGKα-selective inhibitor, CU-3, induced both cancer cell apoptosis and T-cell activation." (PMID 32947951, 2020).